GIT1 (GIT ArfGAP 1)
Description:
GTPase-activating protein for ADP ribosylation factor family members, including ARF1. Multidomain scaffold protein that interacts with numerous proteins and therefore participates in many cellular functions, including receptor internalization, focal adhesion remodeling, and signaling by both G protein-coupled receptors and tyrosine kinase receptors (By similarity). Through PAK1 activation, positively regulates microtubule nucleation during interphase. Plays a role in the regulation of cytokinesis; for this function, may act in a pathway also involving ENTR1 and PTPN13. May promote cell motility both by regulating focal complex dynamics and by local activation of RAC1. May act as scaffold for MAPK1/3 signal transduction in focal adhesions. Recruits MAPK1/3/ERK1/2 to focal adhesions after EGF stimulation via a Src-dependent pathway, hence stimulating cell migration. Plays a role in brain development and function. Involved in the regulation of spine density and synaptic plasticity that is required for processes involved in learning (By similarity). Plays an important role in dendritic spine morphogenesis and synapse formation. In hippocampal neurons, recruits guanine nucleotide exchange factors (GEFs), such as ARHGEF7/beta-PIX, to the synaptic membrane. These in turn locally activate RAC1, which is an essential step for spine morphogenesis and synapse formation. May contribute to the organization of presynaptic active zones through oligomerization and formation of a Piccolo/PCLO-based protein network, which includes ARHGEF7/beta-PIX and FAK1 (By similarity). In neurons, through its interaction with liprin-alpha family members, may be required for AMPA receptor (GRIA2/3) proper targeting to the cell membrane (By similarity). In complex with GABA(A) receptors and ARHGEF7, plays a crucial role in regulating GABA(A) receptor synaptic stability, maintaining GPHN/gephyrin scaffolds and hence GABAergic inhibitory synaptic transmission, by locally coordinating RAC1 and PAK1 downstream effector activity, leading to F-actin stabilization. May also be important for RAC1 downstream signaling pathway through PAK3 and regulation of neuronal inhibitory transmission at presynaptic input (By similarity). Required for successful bone regeneration during fracture healing (By similarity). The function in intramembranous ossification may, at least partly, exerted by macrophages in which GIT1 is a key negative regulator of redox homeostasis, IL1B production, and glycolysis, acting through the ERK1/2/NRF2/NFE2L2 axis (By similarity). May play a role in angiogenesis during fracture healing (By similarity). In this process, may regulate activation of the canonical NF-kappa-B signal in bone mesenchymal stem cells by enhancing the interaction between NEMO and 'Lys-63'-ubiquitinated RIPK1/RIP1, eventually leading to enhanced production of VEGFA and others angiogenic factors. Essential for VEGF signaling through the activation of phospholipase C-gamma and ERK1/2, hence may control endothelial cell proliferation and angiogenesis.
Synonyms: p95-APP1
Tractability: PROTAC: ubiquitination databases record sites on it; its protein half-life has been measured.
Gene: Protein-coding gene on chromosome 17 (29,573,475 to 29,594,054, reverse strand). Ensembl gene ENSG00000108262.
Subcellular location: Cytoplasm; Synapse; Presynapse; Postsynapse; Postsynaptic density; Cell junction, focal adhesion; Cell projection, lamellipodium; Cytoplasm, cytoskeleton, microtubule organizing center, centrosome; Cytoplasm, cytoskeleton, spindle pole
Subcellular location (Human Protein Atlas): Cytosol; Focal adhesion sites; Mitochondria
Pathways (Reactome):
Signal Transduction: CDC42 GTPase cycle; RAC1 GTPase cycle; RAC2 GTPase cycle; RAC3 GTPase cycle; RHOJ GTPase cycle; RHOQ GTPase cycle; RHOU GTPase cycle; RHOV GTPase cycle
Developmental Biology: Ephrin signaling
Neuronal System: Activation of RAC1 downstream of NMDARs
Gene Ontology:
Molecular function: gamma-tubulin binding; protein binding; GTPase activator activity; small GTPase binding; identical protein binding; protein phosphatase binding; protein tyrosine kinase binding; scaffold protein binding; signaling receptor complex adaptor activity; structural constituent of postsynaptic specialization
Biological process: positive regulation of microtubule nucleation; regulation of cytokinesis; brain development; cell redox homeostasis; cellular response to lipopolysaccharide; intramembranous ossification; negative regulation of glycolytic process; negative regulation of inflammatory response to wounding; negative regulation of interleukin-1 beta production; regulation of ARF protein signal transduction; regulation of G protein-coupled receptor signaling pathway; synaptic vesicle recycling; cellular response to epidermal growth factor stimulus; maintenance of postsynaptic specialization structure; negative regulation of ARF protein signal transduction; neurotransmitter receptor localization to postsynaptic specialization membrane; positive regulation of AMPA glutamate receptor clustering; positive regulation of receptor catabolic process
Cellular component: centrosome; cytoplasm; cytosol; focal adhesion; membrane; mitotic spindle pole; synapse; neuron projection; postsynapse; postsynaptic density; presynapse; dendrite; endosome; excitatory synapse; GABA-ergic synapse; glutamatergic synapse; growth cone; inhibitory synapse; lamellipodium; presynaptic active zone; protein-containing complex; spindle pole
Genetic constraint (gnomAD): Loss-of-function variants: 13 observed, 80.58 expected, observed/expected ratio (o/e) 0.16, 90% interval 0.1 to 0.26. The upper end of that interval is the gene's LOEUF score, 0.26, which puts it in group 1 of 6, group 1 being the genes least tolerant of losing a copy. Missense variants: 681 observed, 968.31 expected, observed/expected ratio (o/e) 0.7, 90% interval 0.66 to 0.75. Synonymous variants: 393 observed, 404.25 expected, observed/expected ratio (o/e) 0.97, 90% interval 0.89 to 1.06.
Homologues: Orthologues: chimpanzee GIT1 (99% identical), pig GIT1 (99% identical), dog GIT1 (99% identical), mouse Git1 (98% identical), rat Git1 (97% identical), macaque GIT1 (97% identical), rabbit GIT1 (96% identical), guinea pig GIT1 (94% identical), tropical clawed frog git1 (81% identical), zebrafish git1 (76% identical). Paralogues in human: GIT2 (67% identical), APPL1 (17% identical), ARAP3 (17% identical), APPL2 (16% identical), ARAP2 (16% identical), ARAP1 (14% identical), ASAP2 (14% identical), ASAP1 (14% identical), AGAP3 (12% identical), ASAP3 (12% identical), AGAP1 (12% identical), ACAP3 (12% identical), and 16 more.
Diseases named in the same sentence as GIT1 in open-access papers:
GIT1 is named in the same sentence as 56 diseases in open-access papers, as found by Europe PMC text mining. Sharing a sentence is not in itself a finding about the gene and the disease. The quoted sentences say what the papers report.
breast carcinoma (15 papers, 2014 to 2025). "Low expression of miR-149 and high expression of GIT1 are associated with advanced stage breast cancer and lymph node metastasis." (PMID 29324832, 2018). "From a breast cancer diagnostics perspective, it is interesting to note that the GIT1 protein levels were lower in ER(−) than in ER(+) breast cancer and that lower GIT1 levels in ER(−) breast cancer patients correlated with poor relapse-free survival." (PMID 35318302, 2022). "A study using animals injected via the tail vein with sublines of highly metastatic breast cancer cells reported that inhibition of GIT1 expression reduced cell migration/invasion and lymph node metastasis through FAK and paxillin signalling." (PMID 35318302, 2022). "Here the authors show that G protein-coupled receptor kinase-interacting protein 1 (GIT1) negatively regulates Notch signalling and tumour growth in ER- breast cancer by blocking Notch ICD nuclear translocation." (PMID 35318302, 2022). "We found that 17β-oestradiol increased GIT1 immunoreactivity in ER(+) breast cancer cells, whereas fulvestrant and tamoxifen blocked this effect." (PMID 35318302, 2022). "Taken together, these data demonstrated that GIT1 is expressed at lower protein levels in ER(−) breast tumours than ER(+) tumours and that ER(−) breast cancer patients with high levels of GIT1 have a better prognosis than those with low levels." (PMID 35318302, 2022). "We sought to investigate the protein expression pattern and role of GIT1 in tumour samples from patients with ER(+) and ER(−) breast cancer." (PMID 35318302, 2022). "In conclusion, the discovery of the GIT1-Notch axis in ER(−) breast cancer sheds light on the control of Notch signalling and identifies GIT1 as a guardian against breast cancer growth." (PMID 35318302, 2022). "A proteomic analysis also showed lower protein levels of GIT1 in patients with ER(−) breast cancer compared to patients with ER(+) breast cancer." (PMID 35318302, 2022). "miR-149 suppresses breast cancer cell invasion and metastasis by targeting GIT1 (G-protein-coupled receptor kinase-interacting protein 1)." (PMID 29324832, 2018). "Despite the clear evidence shown here that GIT1 is down-regulated in both lymph node and distant metastasis in breast cancer another study reported an increase in GIT1 expression between primary tumours and lymph node metastasis." (PMID 29862012, 2017). "We extended these studies to other subtypes of breast cancer by looking at cohorts from publicly available databases (n= 3452) and found that GIT1 is over-expressed in breast cancer and its expression associates inversely with ER status." (PMID 29862012, 2017). "Although Chanet al. reported that GIT1 is over-expressed in lymph nodes when compared to primary breast cancer, very few cases were examined by qRT-PCR (<30) and even fewer (<10) by IHC6, the most prevalent biomarker detection technique used in clinics." (PMID 29862012, 2017). "As immunohistochemistry (IHC) exhibits greater potential for clinical application we decided to evaluate GIT1 immunoreactivity in an extensive cohort of ER+ breast cancer cases with synchronous lymph node (LN) involvement (n=140)." (PMID 29862012, 2017). "In the current study, we ascertained the clinical relevance of GIT1 expression by IHC in a cohort of ER positive breast cancer samples with involved synchronous lymph nodes." (PMID 29862012, 2017). "The expression of G-protein-coupled receptor kinase-interacting protein 1 (GIT1) has recently been shown to be an indicator of advanced stage breast cancer." (PMID 29862012, 2017). "For example, miR-149 suppresses metastasis of breast cancer via directly targeting GIT1 expression which compromises integrin signaling." (PMID 26498692, 2015).
breast carcinoma (continued). "To determine whether GIT1 expression could predict prognosis in breast cancer patients, we performed a Kaplan–Meier analysis in multiple databases, which revealed a direct correlation between high GIT1 expression and increased relapse-free survival." (PMID 35318302, 2022). "Additionally, we can add GIT1, in addition to HER3, as a MAP3K4 associated protein that is necessary for HRG induced extracellular lactate in MCF-7 breast cancer cells." (PMID 31346208, 2019). "In summary, our study has shown that the expression of GIT1 in breast cancer could serve as a useful biomarker for the management of breast cancer patients in general and for ER+/LN+ patients in particular." (PMID 29862012, 2017). "Furthermore, GIT1 levels were down-regulated between primary sites and distant metastases, and that was true not only in ER+ breast cancer but also other subtypes." (PMID 29862012, 2017). "Therefore, we investigated its expression and prognostic value of GIT1 in a cohort of 140 ER+ breast cancer with synchronous lymph node involvement." (PMID 29862012, 2017). "Notably, GIT1 was unaffected by 17β-oestradiol in ER(−) breast cancer cells." (PMID 35318302, 2022). "Thus, GIT1 appears to have distinct functions in the growth and migration of breast cancer cells." (PMID 35318302, 2022). "We have also implicated pTyr-PAK1 in the regulation of breast cancer cell adhesion and demonstrated that phosphorylation of tyrsines 153, 201 and 285 of PAK1 regulates cell adhesion, contribute to maximal PAK1 kinase activity and increased ability to bind βPIX and GIT1." (PMID 27542844, 2016). "Axon guidance signalling proteins Paxillin (PXN) and Reticulon4 (RTN4) showed increased abundance, while GIT1, GRB2 and SHRANK2 showed decreased abundance in breast cancer cells after co-culture." (PMID 39232464, 2024). "In breast cancer, miR-149 also acts as a suppressor of metastasis by targeting GIT ArfGAP 1 (GIT1) to inhibit integrin signaling." (PMID 37369946, 2023). "Additionally, GIT1 could serve as a biomarker in ER(−) breast cancer." (PMID 35318302, 2022). "Instead, we show that GTPase-activating protein GIT ArfGAP 1 (GIT1) is an SRC effector that regulates YAP/TAZ activity in both melanoma and breast cancer cells." (PMID 30559289, 2019). "Intriguingly, we found a moderate but clear negative correlation between ALDH1 and GIT1 in breast cancer patients (n = 2509, Spearman’s ρ = −0.45, P < 0.0001)." (PMID 35318302, 2022). "In breast cancer, our data revealed that GIT1 directly interacts with the Notch ICD in the cytoplasm, thus preventing nuclear translocation and transcription of Notch downstream target genes." (PMID 35318302, 2022). "Here we show that increased expression levels of GIT1 correlate with high relapse-free survival in oestrogen receptor-negative (ER(-)) breast cancer patients and that GIT1 mediates negative regulation of Notch." (PMID 35318302, 2022). "Differential gene expression analysis between breast cancer patients (n = 2509) with high and low GIT1 levels revealed significantly increased expression of aldehyde dehydrogenase 1 (ALDH1) and C-X-C chemokine receptor type 4 (CXCR4) in the patients with low GIT1." (PMID 35318302, 2022). "Interestingly, we discovered that silencing GIT1 in ER(−) breast cancer cells resulted in an expanded ALDH1+ population and enhanced clonogenic capacity, indicating that GIT1 is a critical negative modulator of ALDH1." (PMID 35318302, 2022).
gastric cancer (8 papers, 2017 to 2025). A primary or metastatic malignant neoplasm involving the stomach. "We screen the library and identify small-molecule inhibitors to interrupt the protein–protein interaction (PPI) of GIT1/β-Pix complex, an unrevealed target involved in gastric cancer metastasis." (PMID 36418900, 2022). "In this manuscript, our study suggested that GIT1 expression is upregulated and its interaction with β-Pix promotes gastric cancer metastasis." (PMID 36418900, 2022). "MiR-122-5p inhibits the proliferation and metastasis of tumour cells by inhibiting GIT1 in gastric cancer." (PMID 35712981, 2022). "We observed GIT1 expression was obviously elevated at the protein level in gastric cancer tissues, as well as in several representative gastric cancer cell lines." (PMID 36418900, 2022). "We focused on GIT1/β-Pix interaction for its potential regulatory function in gastric cancer metastasis." (PMID 36418900, 2022). "GIT1 has been reported to be upregulated in several malignant tumors, such as oral, lung, breast, and gastric cancer." (PMID 33258389, 2021). "Since the candidate compounds could interfere with the GIT1/β-Pix interaction, we next tested whether they could affect gastric cancer cell invasion." (PMID 36418900, 2022). "GIT1 can promote gastric cancer cell proliferation and metastasis." (PMID 34663332, 2021). "miR-122-5p is downregulated in gastric cancer and suppresses gastric tumor proliferation and metastasis by targeting GIT1, suggesting that promoting miR-122-5p function could suppress chronic atrophic gastritis and potentially inhibit the development of gastric cancer." (PMID 40045434, 2025). "Thus, inhibiting GIT1/β-Pix interaction would possess the potential for gastric cancer therapy." (PMID 36418900, 2022). "Moreover, GIT1 expression was also found to be elevated in gastric cancer." (PMID 33258389, 2021). "From screening SMBL, we successfully identify two compounds capable of interrupting the interaction of GIT1/β-Pix complex, an undruggable PPI involved in gastric cancer metastasis." (PMID 36418900, 2022). "Moreover, we tried to determine whether the mutants of GIT1 (GIT1Mut1: GIT1L271A; GIT1Mut2: GIT1L279A) influenced the drug-induced inhibition of gastric cancer cell invasion and Rac1 activation." (PMID 36418900, 2022).